NUDCD1 (NudC domain containing 1)
Synonyms: CML66; FLJ14991; OVA66
Tractability: PROTAC: ubiquitination databases record sites on it; its protein half-life has been measured.
Gene: Protein-coding gene on chromosome 8 (109,240,919 to 109,334,129, reverse strand). Ensembl gene ENSG00000120526.
Subcellular location: Cytoplasm (Isoform 1); Nucleus; Cytoplasm (Isoform 2); Cytoplasm (Isoform 3)
Subcellular location (Human Protein Atlas): Nucleoplasm; Cytosol
Gene Ontology:
Molecular function: protein binding
Cellular component: cytosol; nucleoplasm; cytoplasm; nucleus
Genetic constraint (gnomAD): Loss-of-function variants: 25 observed, 34.46 expected, observed/expected ratio (o/e) 0.73, 90% interval 0.53 to 1.01. The upper end of that interval is the gene's LOEUF score, 1.01, which puts it in group 4 of 6, group 1 being the genes least tolerant of losing a copy. Missense variants: 345 observed, 383.35 expected, observed/expected ratio (o/e) 0.9, 90% interval 0.82 to 0.98. Synonymous variants: 137 observed, 134.73 expected, observed/expected ratio (o/e) 1.02, 90% interval 0.88 to 1.17.
Homologues: Orthologues: chimpanzee NUDCD1 (99% identical), macaque NUDCD1 (98% identical), dog NUDCD1 (94% identical), pig NUDCD1 (94% identical), rabbit NUDCD1 (93% identical), guinea pig NUDCD1 (90% identical), mouse Nudcd1 (90% identical), rat Nudcd1 (90% identical), tropical clawed frog nudcd1 (68% identical), zebrafish nudcd1 (58% identical), Drosophila melanogaster CG10347 (24% identical), Caenorhabditis elegans C44E4.5 (24% identical).
Diseases named in the same sentence as NUDCD1 in open-access papers:
NUDCD1 is named in the same sentence as 48 diseases in open-access papers, as found by Europe PMC text mining. Sharing a sentence is not in itself a finding about the gene and the disease. The quoted sentences say what the papers report.
chronic myelogenous leukemia (5 papers, 2014 to 2023). "NUDCD1 was originally identified in a chronic myelogenous leukemia cDNA expression library and is a highly immunogenic protein." (PMID 37338527, 2023). "NudCD1 is a tumour antigen with a wide immunogenic range, located on human chromosome 8q23.3 and is found on screening the serum of patients with chronic myeloid leukaemia using serological analysis of recombinant tumour cDNA expression libraries." (PMID 36104662, 2022). "NUDCD1 is also expressed abundantly in primary acute myeloid leukaemia cells, acute lymphoid leukaemia cells, and chronic myelogenous leukaemia cells in advanced phase, compared with normal cells." (PMID 30138346, 2018). "NUDCD1 was highly expressed in the cells from meningioma and CML (Chronic myelogenous leukemia), and low in the cells from chondrosarcomas and giant cell tumors." (PMID 37338527, 2023). "In addition to chronic myelogenous leukemia cells, NudCD1 is also overexpressed in lung cancer, melanoma, prostate cancer, pancreatic cancer, colorectal cancer cell lines and tumour tissues, but not in normal human tissues except for the testis and heart tissue." (PMID 36104662, 2022). "NudCD1, also known as CML66 or OVA66, is a protein initially identified as overexpressed in patients with chronic myelogenous leukemia." (PMID 29021621, 2017).
acute myeloid leukaemia (2 papers, 2018 to 2023). "NUDCD1 expression was abnormally expressed in DLBC (Lymphoid neoplasm diffuse large B-cell lymphoma), LAML (Acute myeloid leukemia), THYM (Thymoma) compared with normal tissue and was also present in BRCA subtypes." (PMID 37338527, 2023).
cervical carcinoma (2 papers, 2018 to 2023). A carcinoma arising from either the exocervical squamous epithelium or the endocervical glandular epithelium. "NUDCD1 has been functionally linked to tumorigenesis in pancreatic, lung, colorectal, ovarian and cervical cancer." (PMID 37338527, 2023). "As an oncoprotein upregulated in multiple tumor tissues and cell lines, NUDCD1 has been reported to contribute to ovarian and cervical cancer, colorectal cancer, and renal cell carcinoma." (PMID 37338527, 2023). "With regard to the other genes, NUDCD1 (also known as CML66 or OVA66) has been reported to have an oncogenic function in cervical carcinoma by favouring tumour cell proliferation, invasion, and metastasis associated with multiple pathways." (PMID 30138346, 2018). "NUDCD1 overexpression has been documented for NSCLC, colorectal cancer (CRC), renal carcinoma and ovarian and cervical cancer." (PMID 37338527, 2023).
colorectal cancer (2 papers, 2022 to 2023). A primary or metastatic malignant neoplasm that affects the colon or rectum. "The aim was to explore the possibility of using NudCD1 as a diagnostic and prognostic marker in colorectal cancer." (PMID 36104662, 2022). "The Kaplan–Meier survival analysis showed that patients with high NudCD1 expression in colorectal cancer tissues had a significantly shorter survival time than those with low expression of NudCD1 (P < 0.01)." (PMID 36104662, 2022). "Immunohistochemical staining was used to detect in situ expression of NudCD1 in 100 colorectal cancer tissue samples." (PMID 36104662, 2022). "NudCD1 protein expression in colorectal cancer tissues had a remarkable correlation with tumour differentiation and TNM staging (P < 0.01)." (PMID 36104662, 2022). "This study also found that the survival time of colorectal cancer patients with high expression of NudCD1 protein was significantly shorter than that of patients with low expression of NudCD1 protein." (PMID 36104662, 2022). "The Kaplan–Meier survival analysis was used to assess the correlation between the NudCD1 mRNA expression and the three-year survival of patients with colorectal cancer." (PMID 36104662, 2022). "The impact of NudCD1 on the development of colorectal cancer and the underlying molecular mechanisms were assessed by flow cytometry cell cycle and apoptosis assays after lentiviral overexpression of NudCD1 in two colorectal cancer cell lines." (PMID 36104662, 2022). "This study found that the expression of NudCD1 protein in colorectal cancer tissues was significantly higher than that in normal intestinal tissue, and its expression level was consistent with the progression of colorectal cancer." (PMID 36104662, 2022). "This study showed that the NudCD1 expression level is consistent with the progress of colorectal cancer." (PMID 36104662, 2022). "The chi-square test was used to assess the correlation between NudCD1 protein expression and clinicopathological features in colorectal cancer." (PMID 36104662, 2022). "Compared with normal intestinal tissue (8.00% with high expression), the expression of NudCD1 protein in colorectal cancer tissue was significantly higher (58.00% with high expression, P < 0.01)." (PMID 36104662, 2022). "Results showed that NudCD1 protein expression in colorectal cancer tissue correlated significantly with tumour differentiation and TNM staging (P < 0.01), as well as with invasion by the original tumour and lymph node metastasis (P < 0.05)." (PMID 36104662, 2022). "The Kaplan–Meier survival analysis showed that patients with high NudCD1 expression in colorectal cancer tissues had a significantly shorter survival time than those with low NudCD1 expression (P < 0.01)." (PMID 36104662, 2022). "NudCD1 can serve as a valuable prognostic marker for colorectal cancer." (PMID 36104662, 2022). "The results showed that NudCD1 overexpressing colon cancer HT-29 cells had significantly higher mRNA expressions of BUBR1, MPS1 and LIS1, indicating that NudCD1 promotes the occurrence of colorectal cancer by up-regulating SAC-related genes and the LIS1 pathway." (PMID 36104662, 2022). "We used immunohistochemistry (IHC) to detect in situ NudCD1 expression in paraffin-embedded colorectal cancer tissue and studied the correlation between NudCD1 expression, clinicopathological features and prognosis in colorectal cancer patients." (PMID 36104662, 2022). "In this study, the expression of NudCD1 in colorectal cancer tissue and adjacent normal mucosa was determined by IHC, and the results showed that NudCD1 protein expression was significantly higher (P < 0.01) in colorectal cancer tissues, while normal intestinal tissues had weak or no expression." (PMID 36104662, 2022). "IHC staining was used to detect in situ expression of NudCD1 in colorectal cancer tissues." (PMID 36104662, 2022). "Moreover, NUDCD1 was expressed in several cancers including testicular and colorectal cancer." (PMID 37338527, 2023).
colorectal cancer (continued). "NudCD1 may be an important marker for the prognosis of colorectal cancer." (PMID 36104662, 2022). "We studied colon-cancer cell lines with overexpressed NudCD1 genes to assess changes in the cell cycle, apoptosis, SAC-related gene expression and the LIS1 pathway to explore the possible mechanism of NudCD1 involvement in cell mitosis and abnormal chromosome segregation in colorectal cancer." (PMID 36104662, 2022).
head and neck squamous cell carcinoma (2 papers, 2023). A squamous cell carcinoma that arises from any of the following anatomic sites: lip and oral cavity, nasal cavity, paranasal sinuses, pharynx, larynx, and salivary glands. "Additionally, NUDCD1 overexpression was also associated with poor survival of patients with hepatocellular carcinoma and head and neck squamous cell carcinoma." (PMID 37338527, 2023). "NUDCD1, ENY2, PNO1, CCT4 and PSMD14 are considered to promote the proliferation, invasion and treatment resistance of tumor cells in a variety of cancers, including pancreatic cancer, rectal cancer, liver cancer, breast cancer, glial cancer and head and neck squamous cell carcinoma." (PMID 37827692, 2023).
pancreatic cancer (2 papers, 2021 to 2023). "NudC domain containing 1 (NUDCD1) is an oncoprotein frequently activated or upregulated in various human cancers, but its role in pancreatic cancer (PC) remains unknown." (PMID 34325402, 2021).
adrenocortical cancer (1 paper, 2023). "In contrast, low NUDCD1 alteration frequencies were detected with adrenocortical cancer, cholangiocarcinoma, kidney renal papillary cell carcinoma and thymoma." (PMID 37338527, 2023).
autoimmune atherosclerosis (1 paper, 2025). An autoimmune form of atherosclerosis. "NUDCD1 is located in the cytosol and is thought to be involved in modulation of the immune system process and linked to autoimmune atherosclerosis." (PMID 40534864, 2025).
colon cancer (1 paper, 2022). "The mRNA expression of LIS1, a downstream molecule of NUDC / LIS1 / dynein pathway, was also significantly increased in NudCD1 overexpressed colon cancer cells, whereas the S phase was relatively shortened." (PMID 36104662, 2022). "Compared with the untreated control group, the S phase was shortened in NudCD1 overexpressing cancer cells, indicating that NudCD1 overexpression interfered with DNA replication of colon cancer cells, potentially exacerbating the formation of atypical cancer cells." (PMID 36104662, 2022). "The NudCD1 overexpression colon cancer cells had an apoptosis rate of 2.91% ± 0.73%, which was not significantly different from those without transfection (3.01% ± 0.42%) or those transfected with empty vector (3.02% ± 0.86%, P > 0.05)." (PMID 36104662, 2022).
COVID-19 (1 paper, 2025). A disease caused by infection with severe acute respiratory syndrome coronavirus 2. "A gene variant of NUDCD1 influences COVID-19 severity in Asians through interacting with DHX15 and MAVS, affecting effective response against SARS-CoV-2." (PMID 40534864, 2025). "Of 136 COVID-19 patients in Singapore (of whom 25% had severe disease), a single nucleotide polymorphism rs2980619 (p.L252F substitution) belonging to NudC-Domain-Containing-1 (NUDCD1) was highly-placed." (PMID 40534864, 2025).
glioma (1 paper, 2023). A benign or malignant brain and spinal cord tumor that arises from glial cells (astrocytes, oligodendrocytes, ependymal cells). "Moreover, NUDCD1 expression was also positively correlated to tumor grades in CESC, LGG (Brain lower grade glioma), LIHC and UCEC and negatively correlated to STAD tumor grade." (PMID 37338527, 2023).
melanoma (1 paper, 2023). A malignant, usually aggressive tumor composed of atypical, neoplastic melanocytes. "More importantly, NUDCD1 possessed significant mutation differences between responders and non-responders of ipilimumab therapy in melanoma patents suggesting that the therapeutic effect of this mAb may be predicted by NUDCD1 mutations." (PMID 37338527, 2023). "However, NUDCD1 did possess significant mutation differences between responders and non-responders for anti-CTLA-4 (ipilimumab) therapy for melanoma." (PMID 37338527, 2023).
non-small cell lung carcinoma (1 paper, 2023). A group of at least three distinct histological types of lung cancer, including non-small cell squamous cell carcinoma, adenocarcinoma, and large cell carcinoma. "For example, NUDCD1 promotes tumor angiogenesis and progression through enhancing autocrine VEGF-VEGFR2 signaling and promotes the proliferation and metastasis of non-small cell lung cancer cells through the IGF1R-ERK1/2 activation." (PMID 37338527, 2023).
ovarian serous cystadenocarcinoma (1 paper, 2023). A malignant serous cystic epithelial neoplasm arising from the ovary. "Genetic alterations of NUDCD1 in different tumor samples indicated that the highest alteration frequency (>15%) appeared for patients with ovarian serous cystadenocarcinoma." (PMID 37338527, 2023).
renal cell carcinoma (1 paper, 2023). "NUDCD1 total protein was elevated in ovarian, colon, clear cell RCC (Renal cell carcinoma), UCEC (Uterine corpus endometrial carcinoma) and LUAD compared with normal tissues." (PMID 37338527, 2023).
Thyroid carcinoma (1 paper, 2023). "NUDCD1 mRNA expression in tumor tissues was significantly higher than that in normal tissues for in BRCA, BLCA, HNSC, LUSC, ESCA, LUAD, LIHC (Liver hepatocellular carcinoma), STAD and COAD but not THCA (Thyroid carcinoma)." (PMID 37338527, 2023).
tongue cancer (1 paper, 2019). A malignant neoplasm affecting the tongue. "Interestingly, this analysis also revealed that NUDCD1 that was significantly correlated with all tongue cancer patients, was relevant (p<0.05) in advanced cancers (stage III-IV; n = 81), not in patients with early cancers." (PMID 31310629, 2019). "Alterations in ANO1, NUDCD1, PIK3CA defined survival in tongue cancer patients with nodal metastasis (node+ECS-), while EPS8 is a significant differential in node+ECS- laryngopharyngeal cancers." (PMID 31310629, 2019).
uveal melanoma (1 paper, 2023). A melanoma derived from melanocytes of the uveal tract. "UVM (Uveal melanoma) patients with NUDCD1 methylation had better DSS, OS and PFS than the patients without methylation." (PMID 37338527, 2023).
cancer (9 papers, 2011 to 2023). A tumor composed of atypical neoplastic, often pleomorphic cells that invade other tissues. "In the cancers with higher mutation frequencies, the NUDCD1 mutation was also linked to immune infiltration in UCEC." (PMID 37338527, 2023). "Notably, the mutation frequencies of NUDCD1 appeared to be higher in some cancers such as UCEC and LUAD." (PMID 37338527, 2023). "Together, these analyses using multiple databases confirmed the expression pattern of NUDCD1 across many cancer types." (PMID 37338527, 2023). "NUDCD1 is aberrantly expressed in numerous tumor tissues and cells so we also explored the prognostic relevance of NUDCD1 in cancers." (PMID 37338527, 2023). "To further explore the molecular mechanism of NUDCD1 in human cancers, we established a protein-protein interaction (PPI) network including 50 NUDCD1-interacted proteins derived from STRING." (PMID 37338527, 2023). "Regrettably, prognostic analysis of the NUDCD1 signatures in these 3 cancers revealed that its expression had weak to moderate implications for 1, 3, 5-year survival." (PMID 37338527, 2023). "First, analyses based on TISIDB revealed that high expression of NUDCD1 indicated a shorter OS (overall survival) in 8 types of cancers." (PMID 37338527, 2023). "There were also significant correlations of NUDCD1 CNV with its mRNA expression in most types of cancers with the exception of THCA, LAML and DLBC." (PMID 37338527, 2023). "DNA methylation of genes also plays a key role in the regulation of cancer progress and we used the GSCA database to explore the DNA methylation of NUDCD1 in pan-cancers." (PMID 37338527, 2023). "Based on above, NUDCD1 was correlated with the cancer-related pathways of apoptosis and cell cycle in STAD, so we detected the apoptosis and cycle in AGS and HGC-27 cells." (PMID 37338527, 2023). "Although the prognostic value of NUDCD1 across pan-cancers was weak, the expression of NUDCD1 still significantly affected the survival of many cancers." (PMID 37338527, 2023). "In conjunction with these findings, SARC was the only cancer type which survival was influenced by both the expression and methylation of NUDCD1." (PMID 37338527, 2023). "DNA methylation of NUDCD1 was significantly and negatively correlated with its mRNA expression in most cancers with the exception of GBM, CHOL, LAML, THYM and THCA." (PMID 37338527, 2023). "In the current study, NUDCD1 expression was negatively correlated CTRP and GDSC drug susceptibility in most cancers." (PMID 37338527, 2023). "NUDCD1 has been previously defined as a cancer antigen and is abnormally upregulated in multiple tumors and acts as an oncogene." (PMID 37338527, 2023). "This first pan-cancer analysis for NUDCD1 provides a comprehensive understanding about its roles across various cancer types, especially in STAD." (PMID 37338527, 2023). "NUDCD1 (NudC domain-containing 1) is abnormally activated in multiple tumors and has been identified as a cancer antigen." (PMID 37338527, 2023). "NUDCD1 was associated with expression levels of recognized immune checkpoints (anti-CTLA-4) and immune infiltrates (e.g., CD4+ and CD8+ T cells) in some cancers." (PMID 37338527, 2023). "NUDCD1 was involved in diverse biological processes and it influenced the occurrence and development of cancers." (PMID 37338527, 2023). "In the current study, for the first time, we used the data from public platforms to conduct a pan-cancer analysis of NUDCD1 to understand the role of NUDCD1 in carcinogenesis." (PMID 37338527, 2023). "NUDCD1 (NudC domain-containing 1 also known as CML66 or OVA66) is a 66 kDa protein abnormally activated in multiple tumors and has been identified as a cancer antigen." (PMID 37338527, 2023). "A chi-square test was used to analyse the correlation between the NudCD1 protein expression level of the cancer tissues and clinicopathological features." (PMID 36104662, 2022).